ESRP1 (epithelial splicing regulatory protein 1)
Diseases named in the same sentence as ESRP1 in open-access papers (continued):
Sharing a sentence is not in itself a finding about the gene and the disease.
cancer (continued). "We hypothesized that E2F1 might transcriptionally induce the RBPs other than ESRP1 to support hypoxic adjustments to the cancer spliceome." (PMID 34362878, 2021). "To investigate the mechanism by which ESRP1 affects SCLC chemoresistance, we analyzed the AS events and potential targets regulated by ESRP1 through mRNA transcriptome sequencing and selected several cancer-related targets to analyze the relationship between their exon ratio and ESRP1." (PMID 33495408, 2021). "Therefore, it is evident that cancer cells leverage the plastic nature of ESRP1 expression incongruously based on oxygen availability in the microenvironment, giving rise to phenotypic and functional heterogeneity." (PMID 34362878, 2021). "For instance, ESRP1 has been suggested to drive both oncogenic and tumor-suppressive programs in the context of different cancers." (PMID 34075878, 2021). "Taken together, these data imply that ESRP1 may be a key regulator that controls cancer progression." (PMID 33495408, 2021). "ESRP1 contributes significantly at different stages of cancer progression." (PMID 34362878, 2021). "Although ESRP1 has varying functions in each cancer type, it might be a metastatic suppressor or oncogene in a tissue-dependent manner." (PMID 34828307, 2021). "We have previously shown that the overexpression of Epithelial Splicing Regulatory Protein 1 (ESRP1) can promote cancer traits in CRC cells, by increasing their anchorage-independency and enhancing their clonogenic capacity in vitro, as well as promoting macrometastasis formation in vivo." (PMID 34439247, 2021). "Most of the previous studies focused on down-regulating ESRP1 to promote EMT in cancers." (PMID 32467669, 2020). "In this study, which combined bioinformatics, biochemical and functional approaches as well as clinical data, we characterized a novel post-transcriptional network that links cancer colonization and immune-suppression in tumor microenvironment regulated by high ESRP1 expression in EOC." (PMID 32467669, 2020). "Our data may facilitate the identification of novel ESRP1-driven therapeutic opportunities to selectively target cancer cells." (PMID 31963158, 2020). "High ESRP1 expression may stimulate cancer epithelial cell growth in the colon, as well as, at distant sites promoting CRC progression." (PMID 31440515, 2019). "The difference in the impact of Esrp2 and Esrp1 overexpression on Cdh1 levels at day 5 is consistent with a previous study demonstrating that the knockdown of Esrp paralogs has different effects on Cdh1 expression in the context of cancer cell motility." (PMID 30704403, 2019). "In addition, ESRP1 overexpression has been correlated with liver macrometastasis in murine models, probably due to its ability to promote cancer cell growth at distant sites." (PMID 31440515, 2019). "ESRP1 has been described as a tumor suppressor in several types of cancers." (PMID 28052020, 2017). "Taken together, these results indicate that enforced ESRP1 expression in OC cells regulates both EMT markers and alternative splicing of cancer-associated genes, thereby leading to a switch from mesenchymal to epithelial phenotype, characterized by reduced cell migration." (PMID 28991261, 2017). "Moreover, in human cell cultures and cancer, ESRP1 has been shown to increase cell adhesion and reduce cell motility." (PMID 29180615, 2017). "Maintaining a finely tuned expression of ESRP1 is important in epithelial cells as elevated ESRP1 levels may post-transcriptionally alter expression of genes involved in pathways that synergize to drive cancer, as happens in a subset of CRC." (PMID 28052020, 2017). "Furthermore, low levels of ESRP1 and increased levels of the long version of GPR137 were associated with poorer outcomes for cancer patients." (PMID 28975893, 2017).
cancer (continued). "Interestingly, the genes CDH1, ESRP1 and GRHL2 have been shown to play critical roles in epithelial-mesenchymal transition (EMT), a process associated with metastatic events in cancer and also highly relevant to tumor progression." (PMID 23887935, 2013). "Loss of ESRP1 expression leads to inclusion of these CD44 variable exons, leading to production of variant CD44v protein isoform that is able to activate the PDGFRβ/Stat3 intracellular signalling pathway to promote the formation of a “cancer stem cell” population with mesenchymal properties." (PMID 37752235, 2023). "Thus, the expression pattern of ESRP1 at different stages of cancer progression is phenomenally plastic, and this plasticity seems to play a critical role in the spatiotemporal optimization of cancer spliceome." (PMID 34362878, 2021). "In addition, a miRs panel from two miR families can inhibit ESRP1, may provide an innovative approach for cancer theranostics." (PMID 32467669, 2020). "In addition, ESRP1 suppresses cancer cell motility through distinct mechanisms during EMT." (PMID 31440515, 2019). "It is possible that upregulation of ESRP1 expression not only inhibits EMT, but also induces G1-phase arrest in cancer cells, and thus ESRP1 is likely to be an ideal candidate target for anti-cancer drugs, although more experiments will be needed to support this hypothesis." (PMID 31362365, 2019). "Hence, inhibition of RAC1B generation may be a potential mechanism through which ESRP1 can suppress cancer cell motility." (PMID 30621237, 2019). "Similarly, ESRP1 downregulation promotes cancer cell stemness and metastasis." (PMID 28975893, 2017). "Cancer stem-like cells of solid malignant tumors which highly express CD44v8-10, the variant isoform of CD44 generated by alternative splicing, has a resistance to redox stress by the robust production of glutathione mediated by ESRP1-CD44v-xCT (cystine/glutamate antiporter) axis." (PMID 28289330, 2017). "In addition, OPN promoted cancer cell invasiveness in an ESRP1-dependent manner." (PMID 28300837, 2017). "Research on various cancer cell lines has identified a positive feedback loop between CD44 and ZEB1, which represses ESRP1 gene activity, thereby promoting CD44s splicing and reinforcing EMT." (PMID 40538061, 2025). "This loss contributes to decreased levels of epithelial splicing regulatory protein 1 (ESRP1), an RNA-binding protein critical for the epithelial-mesenchymal transition (EMT) in cancer." (PMID 40014756, 2025). "Therefore, in this review, we summarize the structure, function, and related pathways of ESRP1, focusing on its potential mechanisms in the occurrence of various solid tumors and its clinical significance as a prognostic biomarker and therapeutic target for cancer patients." (PMID 40046628, 2025). "Although ESRP1 shares a similar primary structural organization with its paralog ESRP2, these two proteins have distinct functions in different cancers." (PMID 40046628, 2025). "Thus, ACLY splicing may be component of an ESRP1-dependent program that relates cancer phenotypes." (PMID 38815867, 2024). "A previous study has shown that ESRP1/2 induces the shift from the epithelial splice form of FGFR2 IIIb to the mesenchymal splice form of FGFR2 IIIc, which is important for cancer cell invasion and metastasis." (PMID 37090731, 2023). "From the newly generated lists of RBP-specific AS targets, we selected CD44 and NUMB for further analysis, based both on their ESRP1-specific AS patterns and on their well-established roles in EMT, stemness/differentiation, and cancer progression." (PMID 36346211, 2022). "Although accumulating evidence suggests the downregulation of ESRP1 during the EMT process and the significance of its role in metastasis of many cancer types, the molecular mechanisms underlying its differential expression in each type of human cancer remain unclear." (PMID 36307405, 2022).
cancer (continued). "Here, we have focused on CD44 and NUMB as two ESRP1-specific AS target genes with well-established functional roles in EMT and in cancer invasion and metastasis." (PMID 36346211, 2022). "Transcription of ESRP1, which requires the binding of E2F1, is elevated in many cancer types, but is drastically lowered in cancer cells within hypoxic niches, with the concomitant induction of EMT." (PMID 35158828, 2022). "For instance, SF epithelial splicing regulatory protein 1 (ESRP1) can regulate expression of CD44 isoforms through AS in MESO and other cancers." (PMID 34041868, 2021). "The expression ESRP1 and its paralog ESRP2 is highly plastic, and several up-regulation and down-regulation episodes are seen in the multistep process of cancer progression, pointing out the difficulty in designing therapeutics against these molecules." (PMID 34439247, 2021). "Studies have shown that ESPR1 and RBM5 play an important role in the event of alternative splicing in cancer 42, 43, and the results of GESA also show that ESRP1 and RBM5 are significantly enriched in the spliceosome pathway." (PMID 33976726, 2021). "Subsequent analysis of subgroups of patients with different clinical variables in the TCGA cohort showed that ESRP1 and RBM5 parts showed prognostic differences, but this does not mean that the results are biased, which may be due to data bias, population susceptibility and cancer heterogeneity." (PMID 33976726, 2021). "Positive nuclear ESRP1 and ESRP2 staining was more common in cancers and was recorded in 39 and 42%, respectively, of all analyzable cancers." (PMID 33339518, 2020). "A combined staining for ESRP1 and ESRP2, was detectable in 2503 (21.6%) of 11,597 for ESRP1 and ESRP2 interpretable cancers." (PMID 33339518, 2020). "This is in line with our previous data showing that ESRP1 induces, through AKT1 activation, the release of FGFs in cancer cells, hence activating an autocrine signalling loop." (PMID 31963158, 2020). "In our study, both ESRP1 and ESRP2 were more frequently expressed in ERG-positive than in ERG-negative cancers." (PMID 33339518, 2020). "In EMT, ESRP1 was thought to directly regulate these subtypes such as FGFR2, ENAH, CD44 and CTNND, thereby losing cell-to-cell adhesion and polarity, increasing cancer cell invasion and migration." (PMID 32467669, 2020). "Both ESRP1 and ESRP2 are believed to be responsible for retaining epithelial phenotypes in cancer cells and thus inhibiting EMT." (PMID 33339518, 2020). "The prognostic significance of ESRP1 expression was analyzed for biochemical recurrence (BCR), recurrence-free survival (RFS), overall survival (OS) and cancer-specific survival (CSS) using the Cox proportional-hazards model (p < 0.05)." (PMID 33194621, 2020). "As human CRC cell lines are relevant cancer models for studying gene function, we also interrogated our gene expression dataset, previously generated using a panel of 151 CRC cell lines, for ESRP1 expression." (PMID 28052020, 2017). "Both RAB25 and ESRP1 are strongly downregulated by the expression of ZEB1, the epithelial-mesenchymal transition (EMT) inducer, in a Tetracycline induced model of human cancer." (PMID 26646320, 2016). "Overall, these findings indicate that ESRP1 is a key regulator of the EMT phenotype induced by oncogenic ALK in normal and cancer lung epithelial cells." (PMID 27119231, 2016). "Reducing ZEB1 expression increases levels of ESRP1 and RAB25 in human cancer and vice versa, and in our study ZEB1 directly affected transcription of both genes." (PMID 26646320, 2016). "Particularly, ESRP1 was involved in response to ICB, while a cancer cell-specific ASE, i.e. PPP1CB-TAI, could serve as a potential tumor antigen predictive of response to ICB." (PMID 41273175, 2025). "However, homogeneous human cancer cell lines tend to have quite high ACLY PSI, and ESRP1 and 2 are exclusively expressed in epithelial cells." (PMID 38815867, 2024).
cancer (continued). "While ESRP1 and ESRP2 share similar structure features and play similar roles in cancers, they may function differently." (PMID 38110955, 2023). "ESRP1 and ESRP2 belong to the RNA-binding protein RBM family, also known as RBM35A and RBM35B, respectively, and are epithelial-specific splicing regulators that control the splicing process of epithelial-to-mesenchymal transition (EMT) in cancer." (PMID 36052258, 2022). "ZEB1 inhibits the epithelial splicing regulatory protein 1 (ESRP1), triggering a change from the epithelial-specific CD44v isoform to the standard CD44s isoform, which maintains the stemness and mesenchymal characteristics of cancer cells." (PMID 35454770, 2022). "The abnormal expression of splicing factors, including ESRP1 and SF3A1, are known to modify splice site selection, thus generating mRNA isoforms that contribute to the development, progression and therapeutic response of cancers." (PMID 31963158, 2020). "These analyses identified ESRP1 expression, ESRP2 expression as well as our ESRP1/ESRP2 score as independent prognostic parameters in all cancers as well as the subset of ERG-negative and ERG-positive cancers in all four scenarios (p ≤ 0.05)." (PMID 33339518, 2020). "For most of 11 analyzed chromosomal regions, ESRP1 and ESRP2 expression was significantly more common in deleted than in non-deleted cancers in all analyzed cancers (11/11 for ESRP1 and 9/11 for ESRP2, p < 0.03 each, data not shown)." (PMID 33339518, 2020). "For example, the fraction of tumors with detectable ESRP1 expression increased from 35.1% in ERG-negative cancers to 42.8% in ERG-positive cancers and with detectable ESRP2 expression from 36.7% in ERG-negative cancers to 51.6% in ERG-positive cancers." (PMID 33339518, 2020). "Furthermore, there was an autocrine feedback loops among ESRP1, HAS2, CD44, and ZEB1 in the aberrant activation of EMT, which acted in the dynamics of EMT in cancer metastasis." (PMID 32211324, 2020). "Moreover, higher expression of ESRP1/2 was also detected in advanced OSCC and cancer nests in metastatic lymph nodes." (PMID 32957697, 2020). "Correspondingly, certain lung cell lines from the Cancer Cell Line Encyclopedia (CCLE) that highly express TM4SF5 exhibited a positive correlation with ESRP1/2 expression and negative correlation with ZEB2 expression." (PMID 31501417, 2019). "Several splicing factors have been shown to enhance splicing of the CD44 variable exons in cancer, such as SAM68, RBM3 and ESRP1, suggesting that regulation of their expression or activity may underlie CD44 splicing control in CSCs." (PMID 28137272, 2017). "Tumorsphere assays demonstrated that ESRP1 overexpression had no influence on cancer stemness of the cells." (PMID 28300837, 2017). "Interestingly, levels of both RAB25 and ESRP1 mRNA were high when ZEB1 mRNA levels were low and vice versa, which is consistent with a previous report examining other cancers." (PMID 26646320, 2016). "Analysis of genes that are coexpressed with CDH1 (E-cadherin) in microarrays across 917 different cell lines from the cancer cell line encyclopedia demonstrates that the CD44 splicing protein, ESRP1, is one of the most highly correlated genes with CDH1 expression." (PMID 25850653, 2015). "Additionally, ESRP1 was most highly positively correlated with the expression of OVOL1/2 (r = 0.76, 0.84 respectively) in a series of 917 cancer cell lines." (PMID 25850653, 2015). "Furthermore, we describe a critical role for the OVOLs as regulators of cancer cell metastasis, by repressing ZEB1 and inducing ESRP1." (PMID 24124593, 2013). "This regulation may characterize the great majority of cancer cells, as demonstrated by the high correlation between the OVOL-TFs, ESRP1 and E-cad in addition to their inverse correlation with ZEB1 and vimentin in 917 cancer cell lines." (PMID 24124593, 2013). "Thus, when ESRP1/2 are downregulated by ZEB1/2, cancer cells express CD44s alone." (PMID 36140527, 2022).
cancer (continued). "Hence, down-regulation of ESRP1 and ESRP2 in OSCC might be restricted to cells that acquire a motile phenotype during cancer invasion." (PMID 32957697, 2020). "Mechanistically, the ESRP1-mediated alternative splicing of the CD44 mRNA stimulates the cystine transporter (x-CT), which is involved in cysteine uptake and the accumulation of reductive glutathione (GSH); this decreases ROS and thereby prevents cancer cell metastasis." (PMID 32967226, 2020). "It has been shown that ESRP1/2 activation leads to oncogenic activation of several ESRP1/2 target genes such as MAP 3 K7, mTOR, GSK3ß, RB1, CTNND1, E-Cadherin, and CD44, which drive tumor cell proliferation and EMT, key features of advanced and aggressive cancers." (PMID 33339518, 2020). "Although downregulation of ESRP1 or ESRP2 expression during the EMT process has been well documented, their expression levels and the molecular mechanisms underlying their altered expression in human cancer have not been fully elucidated." (PMID 28991261, 2017). "Hence, ESRP1-induced CD44v isoform splicing in CSCs promotes lung metastasis without changing cancer stemness of the cells." (PMID 28300837, 2017). "Interestingly, ESRP1 expression is not correlated with poor survival in a pan-cancer analysis, in contrast to ACLY PSI, suggesting that additional factors may influence ACLY splicing and associated phenotype(s)." (PMID 38815867, 2024). "However, given that ESRP1 plays a dual role in cancer progression, ESRP1 itself may not be a suitable therapeutic target in some cancers, and it is required to consider other effective approaches including targeting its downstream proteins." (PMID 38110955, 2023). "This analysis found 11 proteins immunoprecipitating with ESRP1, among which cell cycle and apoptosis regulator protein 2 (CCAR2 alias DBC1, KIAA1967) was an optimal candidate, which could partly explain how ESRP1 participated in cancer progression in CRC cells." (PMID 31963158, 2020). "Reasons for non-informative cases (n = 5607; 31.6% for ESRP1 and n = 4785; 27.0% for ESRP2) included lack of tissue samples or absence of unequivocal cancer tissue in the TMA spot." (PMID 33339518, 2020). "While ESRP1 was significantly up-regulated in EOC, there was a lack of relevant cancer cell biology behaviorial studies." (PMID 32467669, 2020). "Furthermore, recent studies have demonstrated that ESRP1 is involved in non-EMT processes, thus contributing to cancer progression." (PMID 38110955, 2023). "However, it is not known whether ESRP1 and ESRP2 interact to play a role in cancer progression, and further studies are warranted to elucidate the interplay between ESRP1 and ESRP2." (PMID 38110955, 2023).